CHRNA5 (cholinergic receptor nicotinic alpha 5 subunit)
Diseases named in the same sentence as CHRNA5 in open-access papers (continued):
Sharing a sentence is not in itself a finding about the gene and the disease.
schizophrenia (13 papers, 2016 to 2025). A major psychotic disorder characterized by abnormalities in the perception or expression of reality. "After being stratified by ≥45 years, CHRNA5 variants (rs588765, rs6495306, rs680244 and rs692780) were associated with an increased risk of schizophrenia." (PMID 31342675, 2019). "Recently there has been a greater focus on candidate gene CHRNA5 (OMIM#118505) encoding the α5 subunit of nicotinic acetylcholine receptors (nAChRs) in the studies of schizophrenia pathophysiology." (PMID 31342675, 2019). "Overall, our findings supported that the potential association existed between CHRNA5 polymorphisms and schizophrenia susceptibility in a Chinese population." (PMID 31342675, 2019). "But, few studies have been reported in the correlation between CHRNA5 polymorphisms and schizophrenia." (PMID 31342675, 2019). "In our study, our case–control data provided statistical evidence for a strong association between CHRNA5 (rs17486278, rs588765, rs6495306, rs680244, rs692780) and schizophrenia risk." (PMID 31342675, 2019). "One cis-eQTL, rs16969968, results in a functionally disruptive missense mutation in CHRNA5, a schizophrenia-implicated gene." (PMID 30142156, 2018). "There is modest evidence that this and other eQTLs affecting CHRNA5 expression are associated with schizophrenia and affective disorders." (PMID 30142156, 2018). "TCF4 binding sites were also found at other schizophrenia risk loci including the nicotinic acetylcholine receptor cluster, CHRNA5/CHRNA3/CHRNB4 and SETD1A." (PMID 29228394, 2018). "Similarly, CHRNA5 was identified as a risk gene for schizophrenia using the same analytical approach." (PMID 40082977, 2025). "Furthermore, GWAS found that the risk of schizophrenia was associated with a cluster of genes (CHRNA5, CHRNA3 and CHRNB5) on chromosome 15, which was also suggested to be associated with both early age at onset of cigarette smoking and heavy cigarette smoking." (PMID 32107650, 2020). "To examine whether CHRNA5 may also contribute to schizophrenia in a Chinese population, we selected eight variants in CHRNA5 to perform a case–control study." (PMID 31342675, 2019). "In our study, we investigated the correlations between eight CHRNA5 SNPs and schizophrenia risk." (PMID 31342675, 2019). "The lack of a causal relationship between higher rates of smoking and schizophrenia may be related to the minor allele of the rs1051730 single-nucleotide polymorphism of the CHRNA5–CHRNA3–CHRNB4 region." (PMID 29559947, 2018). "Upon analyzing data from TWAS-hub, CHRNA5 emerged as a significant gene mediating the relationship between schizophrenia and inflammatory activity." (PMID 40082977, 2025). "This study is to explore the potential association between CHRNA5 (OMIM#118505) polymorphisms and schizophrenia susceptibility in a Chinese population." (PMID 31342675, 2019). "In conclusion, our results obtained from a cohort of Chinese schizophrenia patients illustrated that CHRNA5 SNPs (rs17486278, rs588765, rs6495306, rs680244, rs692780) were significantly associated with schizophrenia risk." (PMID 31342675, 2019). "Clearly, further research will be required to unravel the functional effects of cis-acting variants at the CHRNA5/A3/B4 locus with TCF4 and other transcriptional regulators in schizophrenia and other neurodevelopmental disorders." (PMID 29228394, 2018). "Of these genes, the CHRNA5-CHRNA3-CHRNB4 cluster had been found to be associated with CPD2, 3 and other ND related traits, and it was reported to be associated with schizophrenia in the latest schizophrenia GWAS meta-analysis from PGC1." (PMID 27164557, 2016). "TWAS analysis indicated that CHRNA5 potentially mediates inflammatory activities in schizophrenia." (PMID 40082977, 2025). "Notably, decreased activity in CHRNA5-altered mice mirrors the reduced prefrontal cortex activity seen in patients with schizophrenia and addiction." (PMID 40082977, 2025).
alcohol dependence (8 papers, 2012 to 2023). Physical and psychological dependence on alcohol. "SNPs within the cholinergic receptor nicotinic alpha-5 subunit (CHRNA5) gene have also been associated with alcohol dependence." (PMID 35625928, 2022). "Additionally, variants near CHRNA5, that alter CHRNA5 mRNA expression in vivo, alter risk for both nicotine and alcohol dependence." (PMID 24804708, 2014). "Nrx-IV human orthologs (CHRNA5, CHRNA 7) have been implicated in alcohol dependence and natural intronic polymorphism segregating within D. melanogaster has been associated with resistance to alcohol." (PMID 28873409, 2017).
lung adenocarcinoma (8 papers, 2013 to 2024). A carcinoma that arises from the lung and is characterized by the presence of malignant glandular epithelial cells. "CHRNA5 polymorphism is associated with lung adenocarcinoma risk in a population-based series of lung adenocarcinoma patients and healthy controls." (PMID 31956359, 2020). "There were 5 genes with a causal relationship to lung adenocarcinoma, including RNASET2, MPZL2, MPZL3, CHRNA5 and UCKL1." (PMID 38834983, 2024). "Analysis of the lung adenocarcinoma patients with wild-type EGFR in the TCGA database also demonstrated a significant correlation between high expression levels of CHRNA5 mRNA and poor overall survival outcome of patients." (PMID 32957649, 2020). "Differential allelic expression of CHRNA5 was also detected in normal lung tissue and in lung adenocarcinoma; two single nucleotide polymorphisms (rs55853698 and rs55781567) in the 5′UTR of CHRNA5 were associated with significant imbalance in allelic expression ratio." (PMID 24303001, 2013). "However, a quantitative analysis of IREB2 mRNA levels in paired normal lung and lung adenocarcinoma tissue demonstrated the increased expression of CHRNA5, but no change in IREB231." (PMID 26310313, 2015).
cocaine dependence (4 papers, 2008 to 2024). A psychologically and socially impaired state, with or without physiological changes, that develops as a result of using cocaine and which leads to compulsive behaviors to acquire the substance. "In addition to nicotine, rs684513 of CHRNA5 was reported as a risk marker for cocaine dependence in African-Americans." (PMID 38862938, 2024). "We applied this method to correlated SNPs in the cholinergic nicotinic receptor gene cluster CHRNA5-CHRNA3-CHRNB4, in a case-control study of cocaine dependence composed of 504 European-American and 583 African-American samples." (PMID 18759969, 2008).
dependence (4 papers, 2013 to 2018). "Genetic association studies in humans show that gene variants in CHRNA5 influence both ETOH and Nic dependence." (PMID 29513745, 2018).
head and neck cancer (4 papers, 2019 to 2025). A primary or metastatic malignant neoplasm affecting the head and neck. "In addition, recent evidence indicates that nicotine exposure can activate CHRNA5 and the downstream mitogen-activated protein kinase kinase (MEK) and extracellular signal-regulated kinases (ERK) pathway, promoting tumor invasion and metastasis in head and neck cancers." (PMID 41347085, 2025).
melanoma (4 papers, 2016 to 2024). A malignant, usually aggressive tumor composed of atypical, neoplastic melanocytes. "A previous study suggested that CHRNA5 could regulate the migration and invasion ability of melanoma cells." (PMID 35214008, 2022). "In melanoma, CHRNA5 was reported to modulate cancer growth by regulating the Notch1 signaling pathway." (PMID 35214008, 2022).
non-small cell lung carcinoma (4 papers, 2016 to 2024). A group of at least three distinct histological types of lung cancer, including non-small cell squamous cell carcinoma, adenocarcinoma, and large cell carcinoma. "The interaction between CHRNA5 and Ly6E mediates the migration of non-small cell lung cancer cells through the TGF-β1–Smad signalling pathway." (PMID 38879667, 2024).
breast carcinoma (3 papers, 2018 to 2022). "A previous report suggested that CHRNA5 RNAi was associated with cell cycle inhibition, apoptosis, reduced DNA damage response, and increased drug sensitivity in breast cancer." (PMID 35071775, 2022). "Functional analysis of CHRNA5 coexpression profile across CCLE breast cancer cell lines revealed a positive association especially with cell cycle regulation and DNA repair pathways." (PMID 30543688, 2018). "CHRNA5, upregulated in breast cancer, was identified as the secondary estrogen signaling network and exhibited prognostic value in breast cancer." (PMID 35214008, 2022). "In fact, previous studies have already identified the role of CHRNA5 in the resistance to chemotherapy in breast cancer and the resistance to radiotherapy in oral squamous cell carcinoma." (PMID 35214008, 2022). "In support of this, we showed that several chromosomal neighbors of CHRNA5 exhibited high correlation of expression also in breast cancer; interestingly, many of these were also involved in cell cycle and proliferation." (PMID 30543688, 2018). "In the present study, we showed using bioinformatics analyses that CHRNA5 was differentially expressed among breast cancer cell lines and tumors with respect to the level of genomic alterations." (PMID 30543688, 2018). "Our experimental studies demonstrate antiproliferative effects of CHRNA5 depletion in breast cancer cell lines using multiple approaches, i.e., RT-qPCR, Western blotting, and comparative transcriptomics analyses." (PMID 30543688, 2018). "Our study demonstrated a significant antimitotic effect of CHRNA5 RNAi application in breast cancer cell lines, complementing the results of existing RNAi phenotypic screen findings in other cell types." (PMID 30543688, 2018). "We calculated the correlation coefficient between CHRNA5 expression level and the fraction of genome-wide alterations obtained for breast cancer cell lines and breast tumors, respectively, using CCLE and TCGA datasets." (PMID 30543688, 2018). "Overall, our findings suggest that CHRNA5 depletion is associated with anti-proliferation, cell cycle arrest, apoptosis as well as reduced DDR and increased drug sensitivity in breast cancer." (PMID 30543688, 2018). "Herein we first showed the expression of CHRNA5 was variable and positively correlated with the fraction of total genomic alterations in breast cancer cell lines and tumors indicating its potential role in DNA damage response (DDR)." (PMID 30543688, 2018). "We used comparative transcriptomics to test correlation of CHRNA5 RNAi expression signature in MCF7 cells with the expression profiles from CCLE breast cancer cell lines, and from nutlin-3a induced as well as from topoisomerase inhibited MCF7 cells." (PMID 30543688, 2018). "We propose that these observed alterations potentially affecting cell fate and survival could partly be achieved through changes in the cholinergic receptor composition by CHRNA5 RNAi in breast cancer cells." (PMID 30543688, 2018). "We also showed that CHRNA5 RNAi transcriptome correlated negatively with DDR relevant gene expression profile in breast cancer gene expression datasets while the coexposure to topoisomerase inhibitors in the presence of CHRNA5 RNAi enhanced chemosensitivity potentially due to reduced DDR." (PMID 30543688, 2018).
breast carcinoma (continued). "We also observed MCF7 breast cancer cell line expressed multiple CHRNA5 isoforms, all of which could be significantly downregulated by using RNAi molecules." (PMID 30543688, 2018). "However, the expression pattern of CHRNA5 in breast cancer cell lines and its possible relationship with genomic alteration levels, as an indirect measurement of DDR, has not been studied." (PMID 30543688, 2018). "Our study suggests CHRNA5 RNAi is associated with cell cycle inhibition, apoptosis as well as reduced DDR and increased drug sensitivity in breast cancer yet future studies are warranted since dose- and cell line-specific differences exist in response to CHRNA5 depletion." (PMID 30543688, 2018). "Depletion of CHRNA5 has been associated with reduced cell viability, increased apoptosis and alterations in cellular motility in different cancers yet not in breast cancer." (PMID 30543688, 2018). "Moreover, the effects of CHRNA5 depletion by RNAi have yet to be tested on breast cancer cell proliferation, apoptosis, DDR and hence drug sensitivity." (PMID 30543688, 2018). "Our findings reveal that CHRNA5 RNAi could act as a candidate CHEK1 inhibitor leading to enhanced drug sensitivity in breast cancer cells and warrants further studies in different cell lines and cancers." (PMID 30543688, 2018). "A strong positive correlation was observed also between mRNA expressions of CHRNA5 and CHEK1 across breast cancer cell lines and tumors." (PMID 30543688, 2018). "However, there is no study examining the association of CHRNA5 with CHEK1 or DDR in breast cancer." (PMID 30543688, 2018). "We finally demonstrated an enhancement in the chemosensitivity of breast cancer cells to CPT and DOXO in the presence of CHRNA5 RNAi yet in dose- and cell-specific manners." (PMID 30543688, 2018). "We also detected a significant positive correlation between the expression levels of CHRNA5 and CHEK1 in CCLE, TCGA and METABRIC breast cancer datasets." (PMID 30543688, 2018). "The observed positive correlations between CHRNA5 and CHEK1 mRNA expression levels in CCLE, TCGA and METABRIC breast cancer datasets are supportive of CHRNA5 RNAi findings in MCF7." (PMID 30543688, 2018). "Among the breast cancer cell lines used in the present study MCF7 exhibited high expression values and had an amplified CHRNA5 locus while the expression of BT20 was higher than that of MDA-MB-231 based on the CCLE dataset." (PMID 30543688, 2018). "Comparison of the co-expression profile of CHRNA5 expression across 59 CCLE breast cancer cell lines with the logFC values from CHRNA5 RNAi profile revealed a highly significant negative correlation and association (r = -0.33, p = 3.8E-48)." (PMID 30543688, 2018). "In addition, the correlation of mRNA expressions of CHRNA5 and CHEK1 among breast cancer cell lines and tumors was highly significant." (PMID 30543688, 2018). "Our findings supported that transcriptomic changes associated with the CHRNA5 siRNA-1 may not be specific to MCF7 cells and could be extended to a large set of breast cancer cell lines." (PMID 30543688, 2018).
COVID-19 (3 papers, 2023 to 2025). A disease caused by infection with severe acute respiratory syndrome coronavirus 2. "COVID-19 patients and smokers’ carriers of one or two copies of the risk allele (rs16969968/A) in CHRNA5 have high ESR and a positive correlation between fibrinogen and C-reactive protein." (PMID 37372959, 2023). "In addition, we did not have albumin data to evaluate the disease prognosis o severity; however, this is the first study that assessed the variant rs16969968 (CHRNA5) in severe COVID-19." (PMID 37372959, 2023). "This research aims to evaluate the association of the polymorphisms rs16969968 (CHRNA5) and rs3918396 (ADAM33) in patients who developed severe COVID-19." (PMID 37372959, 2023). "This research evaluated the association of the polymorphisms rs16969968 (CHRNA5) and rs3918396 (ADAM33) in patients who developed severe COVID-19." (PMID 37372959, 2023). "Genotype and allele analysis was made comparing smokers vs. non-smokers patients; the codominant model shows that does not exist an association between rs16969968 (CHRNA5) and rs3918396 (ADAM33) and COVID-19." (PMID 37372959, 2023).
gastric cancer (3 papers, 2018 to 2023). A primary or metastatic malignant neoplasm involving the stomach. "The reduced sensitivity of gastric cancer to cisplatin under the influence of nicotine was largely blocked by siRNA targeting the CHRNA5 gene, which encodes α5 subunit of nAChR." (PMID 32272633, 2020). "The α5 gene CHRNA5 mRNA is upregulated in several types of cancer, including lung, prostate, colorectal, and stomach cancer, and cancer severity is correlated with smoking." (PMID 37566079, 2023). "The resultant CHRNA5 isoforms are shown to be elevated in lung and gastric cancers also making CHRNA5 a potential cancer biomarker." (PMID 30543688, 2018). "CHRNA5 can have potential implications in drug sensitivity since a recent study in gastric cancer shows that depletion of CHRNA5 hinders the pro-proliferative role of nicotine and resensitizes cells to cisplatin." (PMID 30543688, 2018).
lung diseases (3 papers, 2015 to 2021). "By integrating genetic and epigenetic data, we found that altered DNA methylation and gene expression of CHRNA5 have putatively causal effects on lung diseases." (PMID 33752734, 2021). "Using a bidirectional MR approach, we found evidence that DNA methylation and cigarette smoking have mutual effects on CHRNA5 that in turn influence risk for lung disease." (PMID 33752734, 2021). "Our findings highlight CHRNA5 as a potential therapeutic target for lung diseases and also for smoking cessation." (PMID 33752734, 2021). "IREB2 is located in the region near the CHRNA3/CHRNA5/CHRNAB4 genes cluster with a possible role of lung diseases development." (PMID 26310313, 2015). "To explore the effects of gene expression of CHRNA5, AMICA1, and AHRR on lung diseases, we conducted MR using expression of these three genes as the exposure, cis eQTLs of these genes from FHS whole blood as the instrumental variables, and lung disease traits as the outcomes." (PMID 33752734, 2021).
oral squamous cell carcinoma (3 papers, 2022 to 2025). "In oral squamous cell carcinoma, CHRNA5 was reported to regulate the activity of the E2F signaling pathway, a critical regulator of cell cycle and stemness properties (33986804), contributing to tumor growth and treatment resistance." (PMID 35214008, 2022). "Another study found that CHRNA5 could promote radioresistance via regulating E2F transcription factor activity in oral squamous cell carcinoma." (PMID 35214008, 2022).
depression (2 papers, 2022 to 2024). "A recent study examining sex differences in pleiotropic effects for depression and smoking found pleiotropic effects of FKBP5 on depression and smoking initiation among all participants and pleiotropy for NR3C2 and CHRNA5 for depression and cigarettes per day among females." (PMID 38790194, 2024).
hepatocellular carcinoma (2 papers, 2022 to 2024). A malignant tumor that arises from hepatocytes. "In addition, CHRNA5 promotes metastasis and stem cell proliferation in hepatocellular carcinoma by modulating the Hippo signalling pathway." (PMID 38879667, 2024).
lumbar disc herniation (2 papers, 2019 to 2022). "Our data suggest that gene variance in the CHRNA5/CHRNA3 is associated with risk of lumbar disc herniation in the case-control study." (PMID 31362771, 2019). "This study’s aim is to test whether single-nucleotide polymorphisms in the CHRNA5/CHRNA3 gene are associated with lumbar disc herniation risk." (PMID 31362771, 2019).